ST8SIA1 (ST8 alpha-N-acetyl-neuraminide alpha-2,8-sialyltransferase 1)
Description:
Catalyzes the addition of sialic acid in alpha 2,8-linkage to the sialic acid moiety of the ganglioside GM3 to form ganglioside GD3; gangliosides are a subfamily of complex glycosphingolipds that contain one or more residues of sialic acid. Can catalyze the addition of a second alpha-2,8-sialic acid to GD3 to form GT3. Can use GM1b, GD1a and GT1b as acceptor substrates to synthesize GD1c, GT1a and GQ1b respectively. Can synthesize unusual tetra- and pentasialylated lactosylceramide derivatives identified as GQ3 (II3Neu5Ac4-Gg2Cer) and GP3 (II3Neu5Ac5-Gg2Cer) in breast cancer cells.
Synonyms: SIAT8-A; ST8SiaI; SIAT8; SIAT8A; GD3S
Tractability: Antibody: UniProt predicts a signal peptide or a membrane-spanning region. PROTAC: its protein half-life has been measured.
Gene: Protein-coding gene on chromosome 12 (22,063,773 to 22,437,041, reverse strand). Ensembl gene ENSG00000111728.
Subcellular location: Golgi apparatus membrane
Pathways (Reactome):
Metabolism of proteins: Sialic acid metabolism
Gene Ontology:
Molecular function: alpha-N-acetylneuraminate alpha-2,8-sialyltransferase activity; protein binding; sialyltransferase activity
Biological process: carbohydrate metabolic process; glycosphingolipid biosynthetic process; N-glycan processing; oligosaccharide metabolic process; glycoprotein biosynthetic process; sphingolipid metabolic process
Cellular component: Golgi membrane; membrane
Genetic constraint (gnomAD): Loss-of-function variants: 16 observed, 35.36 expected, observed/expected ratio (o/e) 0.45, 90% interval 0.31 to 0.69. The upper end of that interval is the gene's LOEUF score, 0.69, which puts it in group 2 of 6, group 1 being the genes least tolerant of losing a copy. Missense variants: 378 observed, 470.73 expected, observed/expected ratio (o/e) 0.8, 90% interval 0.74 to 0.87. Synonymous variants: 164 observed, 176.72 expected, observed/expected ratio (o/e) 0.93, 90% interval 0.82 to 1.06.
Homologues: Orthologues: chimpanzee ST8SIA1 (100% identical), macaque ST8SIA1 (99% identical), dog ST8SIA1 (98% identical), pig ST8SIA1 (97% identical), rabbit ST8SIA1 (96% identical), guinea pig ST8SIA1 (96% identical), mouse St8sia1 (92% identical), rat St8sia1 (91% identical), zebrafish st8sia1 (59% identical), tropical clawed frog st8sia1 (47% identical). Paralogues in human: ST8SIA6 (38% identical), ST8SIA5 (37% identical), ST8SIA2 (29% identical), ST8SIA3 (28% identical), ST8SIA4 (26% identical).
Diseases named in the same sentence as ST8SIA1 in open-access papers:
ST8SIA1 is named in the same sentence as 48 diseases in open-access papers, as found by Europe PMC text mining. Sharing a sentence is not in itself a finding about the gene and the disease. The quoted sentences say what the papers report.
breast carcinoma (32 papers, 2012 to 2025). "Reduced ST8SIA1 expression decreased stemness in glioblastoma, whereas the high expression of ST8SIA1 is associated with enhanced tumorigenicity in breast cancer." (PMID 38893185, 2024). "Firstly, in silico analysis suggested that the hypomethylation of ST8SIA1 gene is linked to ST8SIA1 overexpression in the most aggressive types of breast cancer cell lines and tissues tested." (PMID 35267607, 2022). "In breast cancer, high ST8SIA1 expression has been associated with poor prognosis and high histopathological grading." (PMID 35267607, 2022). "Increased mRNA expression of ST3GAL2, as well as ST3GAL5 and ST8SIA1, was also observed in breast cancer stem cells which is eventually linked to increased expression of gangliosides in these cells." (PMID 34975914, 2021). "Recent studies analyzing data from The Cancer Genome Atlas (TCGA) showed an association of high ST8Sia1 expression levels in breast cancer with poor patient survival, which is eventually linked to epigenetic hypomethylation of the ST8SIA1 gene." (PMID 34975914, 2021). "In clinical studies by M. Kaufmann's group, GD3 synthase (GD3S; glycosyltransferase encoded by the ST8SIA1 gene) was more highly expressed in estrogen receptor (ER)-negative breast tumors, and had prognostic significance for ER status-dependent breast cancer." (PMID 28537895, 2017). "Interestingly, ST8SIA1 positively regulated the expression of several breast cancer stem-like cells (BCSC)-associated genes, such as BCL11A, FOXC1, CXCR4, PDGFRβ and SOX2." (PMID 33921986, 2021). "Thus, high expression of ST8SIA1 could increase the risk for poor OS in breast cancer patients and particularly increased the risk for poor DFS in TNBC patients." (PMID 33260650, 2020). "In breast cancer cells, the core promoter of ST8SIA1 contains two putative estrogen response elements (ERE) and a NF-κB binding site critical for promoter activity." (PMID 35267607, 2022). "In ERα positive breast cancer cells, estradiol represses ST8SIA1 expression by inhibiting p65 and p50 nucleus localization and NF-κB binding to the ST8SIA1 promoter." (PMID 35267607, 2022). "ST8Sia1 overexpression has been shown to bypass the need of serum for cell growth and to enhance migratory properties of breast cancer and glioma cell lines." (PMID 34975914, 2021). "A specific STI against ST8SIA1 is an unmet clinical need for breast cancer and TNBC treatment to address in a future study." (PMID 33260650, 2020). "This study provides a valuable analysis of STs based on clinical patient data and indicates ST8SIA1 as a potential therapeutic target for breast cancer and TNBC patients, particularly in the future." (PMID 33260650, 2020). "Further in vitro and clinical studies are required to verify the expression and function of ST8SIA1 beside the GO analysis and other members of STs to provide another therapeutic approach for breast cancer in the future." (PMID 33260650, 2020). "In this study, we described the main ST8SIA1 transcript expressed in breast cancer tumors and cell lines and we characterized the core promoter of this gene." (PMID 23626833, 2013).
breast carcinoma (continued). "The mutation of NFκB binding site led to a significant decrease of luciferase activity (30%), demonstrating NFκB to be involved in ST8SIA1 promoter activity in breast cancer cells." (PMID 23626833, 2013). "We also showed that estradiol repressed endogenous ST8SIA1 mRNA expression as well as ST8SIA1 core promoter activity by preventing NFκB binding in two human breast cancer cell lines expressing Estrogen Receptor alpha (ERα)." (PMID 23626833, 2013). "Altogether, these data show the role of NFκB in transcriptional activation of ST8SIA1 promoter in breast cancer cells and suggest that estradiol inhibits NFκB-mediated activation by preventing p50 and p65 NFκB subunits translocation into the nucleus." (PMID 23626833, 2013). "The 5′-UTR of ST8SIA1 transcripts was analyzed in Hs578T cell line (expressing ST8SIA1 at higher level than others tested breast cancer cell lines) and 20 tumor samples of ER-negative IDC." (PMID 23626833, 2013). "To elucidate the molecular mechanisms leading to over-expression of GD3S in breast cancer, we have undertaken the study of the transcriptional regulation of the GD3S coding gene, ST8SIA1, in breast cancer cells." (PMID 23626833, 2013). "We characterized the corresponding core promoter in Hs578T breast cancer cells and showed that estradiol decreases ST8SIA1 mRNA expression in ER-positive MCF-7 cells and ERα-transfected ER-negative Hs578T cells." (PMID 23626833, 2013). "In breast cancer, ST8SIA1 regulates the EMT process, tumor growth, and metastasis." (PMID 39084491, 2024). "Consequently, the promoter region of the ST8SIA1 gene has been studied in various cell types, such as melanoma, glioblastoma, neuroblastoma, and breast cancer cell lines." (PMID 35267607, 2022). "In particular, high ST8SIA1 expression was observed in patients with the basal-like breast cancer subtype (together with high MET oncogene expression), as well as in breast cancer stem cells (CSC), compared to non-CSCs, which exhibit lower motility and lower mammosphere formation." (PMID 35267607, 2022). "High expression of ST8SIA1 displayed significant association with poor OS and indicated higher risk for poor OS in all breast cancer patients, TNBC, and non-TNBC patients." (PMID 33260650, 2020). "In summary, we conducted a comprehensive analysis of STs from the clinical database and identified ST8SIA1 as a crucial survival-related ST, which might be a potential therapeutic target for breast cancer and TNBC patients." (PMID 33260650, 2020). "However, NFκB was shown to be involved in ST8SIA1 transcriptional activation and we demonstrated that estradiol prevents NFκB to bind to ST8SIA1 core promoter in ERα expressing breast cancer cells by inhibiting p65 and p50 nucleus localization." (PMID 23626833, 2013). "Given that ST8SIA1 is over-expressed in ER-negative breast tumors and that its core promoter contains two putative sites for ERα binding, we investigated the effect of estradiol on ST8SIA1 mRNA expression in breast cancer cell lines MCF-7 and Hs578T." (PMID 23626833, 2013). "Thus, ST8SIA1 affects the survival of breast cancer patients, particularly those with TNBC." (PMID 33260650, 2020). "Thus, from the literature and our comprehensive study, survival-related STs of ST8SIA1 may be a novel and crucial therapeutic target in breast cancer, especially for TNBC patients." (PMID 33260650, 2020). "ST8SIA1 has also been suggested to be important for the initiation and maintenance of EMT in MDA-MB-231 breast cancer cells." (PMID 39329960, 2024). "In the same GD2+ breast cancer cells, FAK and 4E-BP1 were more phosphorylated compared to the GD2 cells, suggesting that FAK–AKT–ERK–mTOR signaling is regulated by ST8SIA1." (PMID 33418847, 2021). "Battula and coworkers discovered that ganglioside GD2 expression defined breast cancer stem cells (BCSCs) and ST8SIA1 regulated GD2 expression and breast cancer stem cell (BCSC) function by activation of the FAK-AKT-mTOR signaling pathway." (PMID 34540690, 2021).
breast carcinoma (continued). "Sarkar and colleagues demonstrated that ST8SIA1 (GD3 synthase) modulates EMT through activation of c-Met and is required for breast cancer cell migration, invasion and metastasis formation in vivo." (PMID 33921986, 2021). "CRISPR-knockout of ST8SIA1, the key enzyme of GD3, GD2, and GD1 expression in these breast cancer stem-like cells, inhibited metastasis and mammosphere formation in vivo." (PMID 33418847, 2021). "In breast cancer, CD109, ID4, and ST8SIA1 are involved in the maintenance of stem cell phenotype, whereas NR4A1 promotes TGF-β-induced EMT and invasion." (PMID 32679794, 2020). "Ganglioside GD2 was also identified as a putative marker of CD44hiCD24lo breast cancer stem cells (CSC) capable of initiating tumors, and several GT genes involved in GD2 biosynthesis (ST3GAL5, B4GALNT1, and ST8SIA1) are highly expressed in CSC." (PMID 29698439, 2018). "Knockdown of the genes for GD2 synthase (B4GALNT1) and GD3S (ST8SIA1) significantly reduced GD2/GD3 expression and reversed the stem cell phenotype (e.g. mammosphere formation and enhanced motility) of breast cancer cells." (PMID 28537895, 2017). "As demonstrated for melanoma, neuroblastoma and breast cancer, the transcription of the GD3 synthase gene (ST8SIA1) is activated by NF-κB pathway upon TNF stimulation." (PMID 27916834, 2016). "The inhibition of GD3 synthase (ST8SIA1) using shRNA or triptolide suppresses the invasion and motility of breast cancer cells and metastasis in mice, while its inhibition does not affect cell proliferation rates in vitro." (PMID 39329960, 2024). "We evaluated gene expression data in TNBC and non-TNBC breast cancer samples using the TCGA dataset and observed higher expressions of ST8SIA1 and B4GALNT1 genes, and a higher score of the 2-gene signature in TNBC." (PMID 32486168, 2020). "In this prospect, the transcriptional regulation of GD3S gene (ST8SIA1), the key enzyme involved in the biosynthesis of b-and c-series gangliosides, has been well described in melanoma, neuroblastoma and breast cancer cells; highlighting a crucial role of NF-κB in activating this gene." (PMID 27916834, 2016). "Reassuringly, our results suggest that TAM treatment of breast cancer patients is unlikely to induce the expression of possibly deleterious complex gangliosides via ST8SIA1 induction in ER-positive breast cancer tumors." (PMID 23626833, 2013). "Moreover, overexpression of ST8 alpha-N-acetyl-neuraminide alpha-2,8-sialyltransferase 1 (ST8SIA1) can increase the tumor cell proliferation, migration, and invasion in prostate cancer, colorectal cancer, and breast cancer via the promotion of the FAK‐AKT‐mTOR signaling pathway." (PMID 35715800, 2022). "Thus, ST8SIA1 is a crucial survival-related ST in breast cancer, regardless of the ER receptor status." (PMID 33260650, 2020).
melanoma (19 papers, 2013 to 2024). A malignant, usually aggressive tumor composed of atypical, neoplastic melanocytes. "We did not observe association between AJCC Stage (8th ed), primary melanoma prognostic factors such as ulceration, Breslow depth, or age at diagnosis, and ST8SIA1 expression." (PMID 32358995, 2020). "The brain‐metastasizing melanoma cell variant (YDFR.CB3) expressed higher mRNA levels of ST8SIA1 than cells from the corresponding parental cutaneous variant (YDFR.C)." (PMID 32358995, 2020). "However, we observed a significant higher ST8SIA1 expression in melanoma patients with BRAF V600e mutation compared to those that were triple WT (wild type of BRAF, NRAS, and NF1 mutations) or NRAS mutation(s) alone." (PMID 32358995, 2020). "However, we compared PRM melanoma with high or low ST8SIA1 expression to determine associations with standard prognostic clinical and pathology factors." (PMID 32358995, 2020). "In a comparable investigation, human melanoma cells of the SK-MEL-28 cell line were genetically modified by introducing ST8SIA1 and B4GALNT1 genes to overexpress GD2." (PMID 38089042, 2023). "And ST8SIA1 was significantly enhanced in melanoma brain metastasis, and ST8SIA1 expression increased the levels of ganglioside GD3 on the cell surface." (PMID 34738863, 2021). "In melanoma brain metastases, it was shown that ST8SIA1 (GD3 synthases) is upregulated and the GD3 expression is increased, which was associated with a bad prognosis." (PMID 34943806, 2021). "ST8SIA1 expression was assessed in clinically well‐annotated melanoma patients from multicenters with AJCC stage III B‐D LNM (n = 58) with 14‐year follow‐up." (PMID 32358995, 2020). "Using RNA‐ISH on FFPE specimens, we evaluated ST8SIA1 expression in primary melanomas (PRM) (n = 23), LNM and visceral metastasis (n = 45), and MBM (n = 39)." (PMID 32358995, 2020). "Icaritin‐mediated downregulation of p50 offers new strategies for targeting ST8SIA1 to reduce melanoma aggressiveness." (PMID 32358995, 2020). "We then performed analysis on patients with LNM because of the differential expression of ST8SIA1 and the availability of long‐term clinical follow‐up available in the TCGA melanoma dataset in a multicenter setting." (PMID 32358995, 2020). "In a nude mouse human xenograft melanoma brain metastasis model, MBM variants had higher ST8SIA1 expression than their respective cutaneous melanoma variants." (PMID 32358995, 2020). "The ST8 alpha-N-acetyl-neuraminide alpha-2, 8-sialyltransferase 1 (ST8SIA 1) gene was the most upregulated in melanoma cell lines in NCI-60 Cell Miner database." (PMID 31611597, 2019). "A functional NFκB binding site at −777/−762 pb upstream the ATG was shown to be essential for ST8SIA1 transcription in melanoma cells." (PMID 23626833, 2013). "Lee and coworkers described a functional NFκB binding site on ST8SIA1 promoter in melanoma cells that we also confirmed by bioinformatic analysis at position −777/−762." (PMID 23626833, 2013). "The 5′-UTR of ST8SIA1 transcripts were previously reported in melanoma, glioblastoma and neuroblastoma cell lines, showing a unique transcript, called T1, with several TSS within the first exon E1, from −400 to −650 bp upstream the ATG." (PMID 23626833, 2013). "ST8SIA1 overexpression enhanced cell proliferation and colony formation in melanoma cells." (PMID 35873547, 2022). "Therefore, we assessed for a potential role of icaritin in controlling ST8SIA1 expression in melanoma cells." (PMID 32358995, 2020). "Downregulation of ST8SIA1 inhibited melanoma cell proliferation in cultures." (PMID 32358995, 2020). "Moreover, decreasing ST8SIA1 expression by siRNA‐mediated KD suppressed melanoma cell proliferation." (PMID 32358995, 2020). "Thus, we assessed the association between ST8SIA1 expression in LNM and OS by using the TCGA cohorts of stage III B‐D melanoma patients (corrected AJCC 8th ed) with clinically annotated 14‐year follow‐up data and annotated clinicopathologically (n = 58)." (PMID 32358995, 2020).